TCF7L2 (transcription factor 7 like 2)
Diseases named in the same sentence as TCF7L2 in open-access papers (continued):
Sharing a sentence is not in itself a finding about the gene and the disease.
diabetes (continued). "Of the many genes investigated, TCF7L2, a β-catenin bipartite transcription factor, integral to the upregulation of incretin secretion from intestinal endocrine L cells and the proliferation of pancreatic beta cells, has the strongest known association with diabetes." (PMID 24906949, 2014). "Therefore, increased TCF7L2 mRNA expression in diabetes may be a consequence of impaired β-cell function owing to a deficiency of TCF7L2 protein." (PMID 23737909, 2013). "Additionally, we examined whether the observed association between GRS and incident diabetes was driven by rs7901695 in the gene TCF7L2, the strongest diabetic gene reported so far." (PMID 24653947, 2011). "In 2006, first discovered and proposed the TCF7L2 gene, and the study on the association between its polymorphism and T2DM has also become a focus of attention in diabetes mellitus." (PMID 40225014, 2025). "An example is the link between high‐fat diets and specific genetic variations, such as those in the FTO and TCF7L2 genes, which make a person more likely to develop diabetes." (PMID 41019177, 2025). "For example, genotype‐guided diets use genetic variations, such as FTO and TCF7L2, with obesity and glucose metabolism to personalize carbohydrate intake and improve diabetes management." (PMID 41019177, 2025). "TCF7L2 genotyping has the potential to be used in clinical practice to customize diabetes therapy according to a patient’s genetic profile, but more investigation and confirmation are needed." (PMID 40872522, 2025). "Taken together, TCF7L2 reveals great potential as a drug target for the management of microvascular and macrovascular complications of diabetes." (PMID 40116328, 2025). "Polymorphisms of the transcription factor 7-like 2 (TCF7L2), the key downstream effector of Wingless (Wnt) signaling, increase the risk of diabetes mellitus." (PMID 40799516, 2025). "It is important to note that TCF7L2 mRNA is upregulated in islets in diabetes, but TCF7L2 protein levels are downregulated." (PMID 40799516, 2025). "Genetic determinants—including receptor polymorphisms (receptors of GLP1 and GIP), transcriptional regulators (TCF7L2), monogenic diabetes genes, and epigenetic modifications—profoundly influence the entero-insular axis in children." (PMID 40649920, 2025). "The enrichment of TCF7L2, KCNQ1, and CDKAL1 variants in specific subtypes highlights the potential for integrating genetic screening into diabetes stratification models." (PMID 41422334, 2025). "It is a crucial player of the WNT signalling and is known to interact with transcriptionfactor7like2(TCF7L2),ForkheadboxproteinO(FOXO), and HIF1A, and previously implicated in the diabetes-cancer link." (PMID 39281650, 2024). "Some genes selected for this study, such as TCF7L2, FTO (rs9939609 variant), and CAPN10, have been shown to be associated with diabetes-related traits such as HbA1c levels, when diets are low in MUFAs and high in SFAs." (PMID 39275336, 2024). "In this study, we screened published literature for studies on the relationship between TCF7L2 and CAPN10 gene polymorphisms and the incidence of diabetes mellitus during pregnancy in different populations." (PMID 38166877, 2024). "For example, instruments are from genes TCF7L2, IGF2BP2, NOTCH2, CDKAL1, PABPC4, FTO and JAZF1, known to be associated with diabetes and that have been further significantly associated with the metabolites." (PMID 39349772, 2024). "For example, among the candidate genes were known susceptibility loci for diabetes (PTPN22, CEP68, RREB1, TCF7L2), coronary artery disease (PSRC1, UNC5C, LPLA), depression (MAD1L1, YLPM1) and insomnia (NMT1)." (PMID 38541061, 2024). "For instance, genes such as TCF7L2 and HK1 located on chromosome 10 have been reported to be significantly associated with the risk of diabetes and HbA1c levels, respectively." (PMID 38274506, 2023).
diabetes (continued). "SNPs in the TCF7L2, KCNQ1, and KCNJ11 genes were studied, and the results confirmed that these three SNPs were associated with all types of diabetes studied, including T2DM, GDM, and PTDM." (PMID 37107681, 2023). "It is well-known that long-term and high dose nicotine administration often leads to a decrease in food consumption, reduction of body weight and diabetes-promoting actions due to Tcf7l2 highly expression in the brain." (PMID 36797299, 2023). "The analysis showed that five SNPs were associated with diabetes: rs1024611 at the CCL2 gene locus, rs6749704 at CCL20, rs333 at CCR5, rs17366743 at ADIPOQ, and rs114758349 at TCF7L2." (PMID 36674502, 2023). "- Genotypic and allelic frequencies and estimates of relative risks for the rs7903146 polymorphic form of TCF7L2 gene in subjects with normal glucose tolerance, Prediabetes and Diabetes." (PMID 36263318, 2022). "Pancreatic pericytes were recently demonstrated to express the diabetes gene transcription factor 7-like 2 (TCF7l2)." (PMID 33981287, 2021). "In astrocytes, knockdown of the lncRNA-TCF7L2 resulted in decreased expression of the parent gene, TCF7L2, as well as alterations in the expression of a series of genes involved in insulin signaling and diabetes." (PMID 34535768, 2021). "Although, TCF7L2 is considered to play function in insulin secretions from pancreas but the exact mechanism for the gene involvement in diabetes development is unclear." (PMID 34394276, 2021). "Recent animal study suggests that TCF7L2 regulates the stimulatory actions of nicotine on a habenula–pancreas axis that links the addictive properties of nicotine to its diabetes-promoting actions." (PMID 34535702, 2021). "Both of the approaches (MR + COLOC and MR + eCAVIAR) have highlighted shared causal SNPs of BMI and diabetes for four genes (TFAP2B, TCF7L2, FTO and ZC3H4)." (PMID 32366963, 2020). "On the contrary, diabetes-related hyperglycemia and/or hyperinsulinemia increases TCF7L2 expression and activates β-catenin/TCF7L2 signaling." (PMID 32651957, 2020). "The C/C cells showed differential binding affinity compared to C/T cells in some previously identified TCF7L2 target genes that are involved in diabetes, such as ACSL5, ATM, AKT2, LEF1, and PDK4." (PMID 32651957, 2020). "In our analysis, both MR + COLOC and MR + eCAVIAR have consistently shown evidence for causal effects on diabetes mediated by BMI for four genes (TFAP2B, TCF7L2, FTO and ZC3H4)." (PMID 32366963, 2020). "Of note, several Maturity Diabetes of the Youth (MODY) and T2D associated genes such as HNF-1α, GCK, and TCF7L2 have splicing variants." (PMID 33088281, 2020). "TCF7L2 and TH-INS are well-known T2D loci and TH-INS has also been reported to be associated with other forms of diabetes (maturity-onset-diabetes of the young and transient neonatal diabetes) and other metabolic phenotypes." (PMID 31324766, 2019). "In other studies, GWAS associations have shown that transcription factor 7-like 2 (TCF7L2), which is part of the Wnt signaling pathway, mediates metabolic syndrome trait susceptibility towards developing diabetes and dyslipidemia." (PMID 31331009, 2019). "Of these genes, TCF7L2 is found to be associated with schizophrenia, which is the best replicated risk factor for T2DM, and exhibits the strongest association to diabetes susceptibility." (PMID 29713286, 2018). "We also found association between CDKN2A/2B (rs10811661), SLC30A8 (rs13266634), and TCF7L2 (rs7903146) and diabetes-related quantitative traits." (PMID 29871606, 2018). "By contrast, a previous study reported an opposite direction of regulating the level of TCF7L2 mRNA (upregulated) and protein (downregulated) in islets in diabetes." (PMID 29713286, 2018).
diabetes (continued). "Among such SNPs, variants at TCF7L2 and CDKAL1 have also been associated with increased risk of cancer in people with diabetes, potentially explaining the higher mortality risk for low BMI values." (PMID 27888288, 2017). "As a study case, TCF7L2 is chosen in that it is a key WNT downstream regulator which is implicated in cancers and diabetes, as well as its alternative splicing generates protein variants with differential promoter-binding and transcriptional activation." (PMID 28499350, 2017). "Several recent reports focused on the relationship of TCF7L2 rs290481 T>C with diabetes mellitus and the results were conflicting." (PMID 29100364, 2017). "Indeed, the loss of insulin secretion due to the loss of function of TCF7L2 in the pancreatic islet and polymorphisms of the human TCF7L2 allele further indicate that the susceptibility and pathogenesis of diabetes mellitus may be caused by disturbance of the Wnt signaling pathway." (PMID 28303247, 2017). "Our data support β-catenin/TCF7L2 as a possible target for diabetes treatment to promote new β-cell formation." (PMID 25950476, 2015). "Transcription factor 7-like 2 (TCF7L2) gene located on chromosome 10q25.3, has been considered as one of the major diabetes susceptibility genes." (PMID 25737773, 2015). "The cumulative evidence for associations between TCF7L2 polymorphisms across multiple ethnicities, together with growing knowledge of WNT/TCF7L2 signaling in β-cells, make it an attractive target for development of novel therapies for diabetes." (PMID 26937418, 2015). "Not only did we find TCF7L2 and KCNQ1 variants to be associated to GDM, but GDM cases reported higher frequency of family history of diabetes than controls." (PMID 25973943, 2015). "An association of T2DM with the calpain 10 (CAPN10) gene was initially identified, and later, its association with the transcription factor 7-like 2 (TCF7L2) gene, whose genetic variants in affected individuals increase the risk of diabetes by ∼1.5 times." (PMID 24894908, 2014). "Risk alleles of all of the 49 investigated T2D loci were associated with incident diabetes with HRs for T2D ≥1, with effect sizes ranging from 1.01 for ADAMTS9 to 1.33 for TCF7L2 per risk allele and p-values <0.05 for 35 of the loci." (PMID 24845081, 2014). "Genome-wide studies identify diabetes susceptibility loci on chromosomes 3q27 and 10q25.3, where adiponectin genes (ADIPOQ or APM1) and TCF7L2 are located, respectively." (PMID 25121131, 2014). "The gene-encoding Transcription 7 Like-2 (TCF7L2, previously called TCF4) is the most important T2D susceptibility gene identified to date, with genetic variants strongly associated with diabetes in all major racial groups." (PMID 23710470, 2013). "In at least two cases discussed in this paper, namely, FTO with obesity and TCF7L2 with diabetes, studies in populations of African descent have facilitated the identification of likely causal variants." (PMID 23577239, 2013). "Little is knownabout the clinical role of TCF7L2 in T2D beyond progression from impairedglucose tolerance to diabetes." (PMID 23617586, 2013). "Briefly, neonatal TCF7L2−/− mice exhibited hypoglycemia, while TCF7L2+/− mice were protected from diabetes." (PMID 22892353, 2012). "Further study is necessary to provide the link between the differential expression patterns for TCF7L2 in the liver and the progression of diabetes in the affected patients." (PMID 23028378, 2012). "Further, the results from our investigation are well in line with numerous other studies consistently showing that TCF7L2 variants rs7903146 and rs12255372 are associated with T2DM and influence the risk of diabetes via pancreatic beta cell dysfunction." (PMID 21423583, 2011). "While some loci, e.g., transcription factor 7-like 2 (TCF7L2), are associated with diabetes and related traits across racial populations, the majority of studies, including ours, have not replicated risk loci across these two racial groups." (PMID 21901158, 2011).
diabetes (continued). "We found that TCF7L2 variants are associated with both T2DM and angiographically diagnosed CAD, and that there are significant interactions between diabetes status and atherogenicity." (PMID 21423583, 2011). "In this study we report that a simple Indian Diabetes Risk Score (IDRS) is more effective and significantly less expensive for screening for undiagnosed T2DM compared to genotyping TCF7L2 SNPs, the strongest genetic marker for T2DM currently available." (PMID 21441683, 2011). "In islets, TCF7L2 has been extensively studied, but generally by analyzing the effect of SNPs on islet function, donor phenotype or probability of developing diabetes." (PMID 20548773, 2010). "Surprisingly, considering the central role of TCF7L2 in stem cell biology, cancer, and diabetes, very little is known of its regulation." (PMID 19924301, 2009). "From 2006 to 2008, study on TCF7L2 gene polymorphisms and its association with T2DM has become the focus in diabetes mellitus, therefore, some meaningful results have reported one by one." (PMID 19228405, 2009). "As the type of diabetes in FCPD is not clearly understood, we used association of TCF7L2 variants with T2D as a marker to decipher the type of diabetes in FCPD." (PMID 18706099, 2008). "Therefore, this study had two objectives: 1) investigate whether TCF7L2 variants are associated with diabetes in the Brazilian population; 2) evaluate how significant is the impact of this association in predicting the prevalent diabetes risk in the general population from Brazil." (PMID 19055834, 2008). "The importance of TCF7L2 as diabetes gene is now very well established across ethnicities but many more genes for diabetes especially in non-white ethnicities still remain to be identified." (PMID 18598350, 2008). "We genotyped the TCF7L2 SNP rs7903146, and correlated genotype with diabetes-related biochemical changes and measures of diabetes complications." (PMID 17181866, 2006). "TCF7L2, which is also a TF, is a key regulator of glucose metabolism and an important component of the Wnt signaling pathway, which is also involved in glucose homeostasis and plays a key role in the aetiology of diabetes." (PMID 41332835, 2025). "Yet, more than a decade after the identification of TCF7L2 as a diabetes gene, the functions of TCF7L2 remain unclear." (PMID 40675550, 2025). "•The diabetes gene Tcf7l2 is crucial for maintaining hepatic zonation." (PMID 40675550, 2025). "The profound, but unexpected, effects of Tcf7l2 on metabolism in mice raised the question of whether TCF7L2 may also have effects beyond diabetes in humans." (PMID 40675550, 2025). "As diabetes is a condition linked to increased cardiovascular risk, it was unsurprising that our work revealed gene interaction between KLFs, particularly KLF-14, and genes associated with diabetic risk factors, such as CAMK1D, HHEX, JAZF1, and TCF7L2." (PMID 38672763, 2024). "Notably, TCF7L2′s ability to modulate PIK3R1 expression suggests its involvement in insulin signaling pathways, potentially mediating diabetes risk through interactions with KLF-14." (PMID 38672763, 2024). "We propose that dysregulation of TCF7L2 gene can result in postprandial hypertriglyceridemia through its actions on the WNT pathway in VAT and could thereby contribute to the associated diabetes risk." (PMID 36263318, 2022). "Recently, a study has suggested that TCF7L2 links nicotine addiction to diabetes in animal models." (PMID 35250867, 2022). "The difference in response to treatment was reported between the TCF7L2 risk allele and the non-risk allele in the early but not in the late stage of diabetes." (PMID 36155628, 2022). "TCF7L2 is associated with susceptibility to GDM independently of the T1D‐risk HLA‐DQB1*0602 allele, autoantibodies to pancreatic β‐cells, and other factors (e.g., maternal age, number of pregnancies, familial history of diabetes, and other genotypes)." (PMID 34612510, 2022).
diabetes (continued). "However, based on the number of studied patients in this region, it seems that a general panel of NOS, TCF7L2, VDR, and PON1 polymorphisms can be used as diagnostic panel markers to identify the susceptible cases to diabetes in Middle East population." (PMID 35366956, 2022). "In detail, we observed that the diabetes‐associated TCF7L2 variants were never present in omCRC patients." (PMID 34668636, 2022). "The transcription factor 7-like 2 (Tcf7l2) gene encodes a key Wnt signaling pathway effector, and its human homologue, TCF7L2, may be a high-risk gene for diabetes." (PMID 33467101, 2021). "Till present, no published data documented the role of TCF7L2 SNPs in diabetes risk for Pashtun language group of Pakistan." (PMID 34394276, 2021). "Prominent examples are well-known diabetes genes such as Tcf7l2 and Abcc8 (also named Sur1)." (PMID 34445304, 2021). "The T allele was identified as a diabetes risk factor, however, the mechanism via which TCF7L2 influenced the risk of diabetes has not yet been completely resolved." (PMID 33810367, 2021). "Moreover, patients carrying the TT genotype of Transcription factor 7-like 2 (TCF7L2), a diabetes-associated gene, in a cardiovascular cohort had poor executive, attention, and processing speed functions compared to those with CC and CT genotypes." (PMID 33352859, 2020). "Thus the identification of elevated serotonin in rs7903146 CT/TT allele carriers in our study offers a new way to explain the link between TCF7L2 and diabetes." (PMID 31492908, 2019). "Transcription factor 7-like 2 (TCF7L2), which previously known as TCF-4, is a major form of transcription factor involved in the downstream WNT signaling and exhibits the strongest association to diabetes susceptibility." (PMID 31312258, 2019). "Wnt/beta-catenin may represent a link between diabetes and cancer, due to the strong genetic association between specific polymorphisms in the TCF7L2 (TCF4) gene and diabetes." (PMID 28298922, 2017). "Therefore, the tcf7l2 mutant presented here appears as a valid tool to study diabetes and its regenerative complications." (PMID 28851992, 2017). "Several recent reports suggested that TCF7L2 rs290481 T>C might play an important role in diabetes mellitus." (PMID 29100364, 2017). "The authors therefore concluded that changes in Tcf7l2 expression in the β cell in man are unlikely to contribute to diabetes risk." (PMID 25355422, 2015). "Interestingly, it was reported that such TCF7L2 is involved in down-regulation of GLP-1 receptor expression found in diabetes." (PMID 25794287, 2015). "The risk of developing diabetes is twice as high in homozygous TCF7L2 risk variant (rs7903146) carriers (TT) compared with non-risk carriers (CC)." (PMID 24906949, 2014). "Alternatively, TCF7L2 may affect cancer independently of diabetes, as the TCF7L2 gene product is involved the Wnt/β-catenin signaling pathway." (PMID 23951231, 2013). "Go back to the list of diabetes related genes and look at TCF7L2 articles." (PMID 23633938, 2013). "Are the biological reasons for matching TCF7L2 to diabetes clearly defined?" (PMID 23633938, 2013). "Thus, the GWAS to date have revealed the involvement of a Wnt ligand (Wnt-5b), Wnt co-receptor (LRP-5) and the Wnt pathway effector TCF7L2 (described further below) in the development of diabetes." (PMID 22892353, 2012). "Although much attention had been given to TCF7L2 function in diabetes related organs such as pancreas, adipocytes and intestine, its role in the brain is largely unknown." (PMID 22247771, 2012). "In the current paper, we find that the diabetes risk marker rs7903146 in TCF7L2 does not impact the ability to lose weight in response to metformin or behavioral intervention." (PMID 21814547, 2011). "Interestingly, when using this definition of SU treatment failure, diabetes duration appeared to be a predictor of treatment failure along with the TCF7L2 genotype." (PMID 21349175, 2011).